VEGFD (vascular endothelial growth factor D)
Diseases named in the same sentence as VEGFD in open-access papers (continued):
Sharing a sentence is not in itself a finding about the gene and the disease.
prostate carcinoma (4 papers, 2006 to 2022). A carcinoma that arises from epithelial cells of the prostate gland. "Interestingly, we found that PKCζ regulates the expression of VEGFD, VEGFA, ANG1, and ANG4 in prostate cancer cells, which may facilitate the generation of aberrant lymphangiogenesis in tumors." (PMID 30705401, 2019).
sarcoma (4 papers, 2012 to 2023). A usually aggressive malignant neoplasm of the soft tissue or bone. "Indeed, VEGFD has been repeatedly described as a direct motility factor for both activated fibroblasts and various sarcoma cells, like chondrosarcoma or Kaposi sarcoma." (PMID 34070472, 2021).
adenoma (3 papers, 2016 to 2021). A neoplasm arising from the epithelium. "For instance, VEGFA is upregulated in adenomas and carcinomas, whereas VEGFD is more abundant in normal tissues." (PMID 27148488, 2016). "Of note, VEGFA, VEGFB, VEGFC, and VEGFD expression is modulated during the adenoma–carcinoma sequence in CRC." (PMID 27148488, 2016).
cholangiocarcinoma (3 papers, 2016 to 2023). A carcinoma that arises from the intrahepatic biliary tree (intrahepatic cholangiocarcinoma) or from the junction, or adjacent to the junction, of the right and left hepatic ducts (hilar cholangiocarcinoma). "The expression of VEGFD tended to be down-regulated in most cancers, except Cholangiocarcinoma (CHOL) and liver hepatocellular carcinoma (LIHC)." (PMID 37852616, 2023).
depression (3 papers, 2018 to 2022). "This is, to our knowledge, the first study to examine VEGFD levels in patients with depression, but in addition to its angiogenic and lymphangiogenic functions, this protein also helps to restore and maintain dendritic complexity in the hippocampus." (PMID 30190686, 2018). "The 6-min walking distance (6MWD), lung function, serum vascular endothelial growth factor-D (VEGF-D) levels, quality of life, and symptoms of anxiety and depression were measured at baseline, 12-week and 24-week follow-up." (PMID 32178705, 2020).
endometrial cancer (3 papers, 2003 to 2023). Primary or metastatic malignant neoplasm involving the endometrium (mucous membrane that lines the endometrial cavity). "Vascular endothelial growth factor-D binds to VEGFR-2 and VEGFR-3, both of which are present in endometrial cancer." (PMID 12942123, 2003).
gallbladder cancer (3 papers, 2016 to 2025). "Moreover, it was demonstrated that a strong relation between TNF-α levels and vascular endothelial growth factor D (VEGF-D) expression in samples of lymphatic metastasis from gallbladder cancer patients." (PMID 31137684, 2019).
invasive breast carcinoma (3 papers, 2013 to 2022). A carcinoma that infiltrates the breast parenchyma. "VEGFD seemed to exert proliferative activity in invasive breast carcinomas." (PMID 35600335, 2022).
pancreatic cancer (3 papers, 2008 to 2022). "However, although VEGFD knockout mice have no obvious phenotype, VEGFD loss-of-function reduces the lymphatic metastasis in an orthotopic in vivo model of human pancreatic cancer and attenuates the pulmonary edema in hyperoxia-induced lung injury." (PMID 35941690, 2022).
pulmonary hypertension (3 papers, 2023 to 2024). Increased pressure within the pulmonary circulation due to lung or heart disorder. "In contrast, several serum levels of soluble factors differed between groups: Endostatin, sVCAM, and VEGFD were increased, and CXCL4, sVEGFR2, and PDGF-AB/BB were decreased in systemic sclerosis–pulmonary hypertension." (PMID 37744051, 2023).
Arthritis (2 papers, 2018 to 2021). Inflammation of a joint. "The swollen joint count (SJC) was identified, among which ICAM-1 and CCL18 were reported relevant to synovial tissue in RA, whereas VEGFD was proposed to participate in the pathogenesis of arthritis." (PMID 34869404, 2021).
asthma (2 papers, 2014 to 2023). "Interestingly, despite elevated levels of VEGFC and VEGFD, decreased lymphatic vessel density is associated with airway edema and fibrotic changes, and has been reported in fatal asthma cases, suggesting that anti-lymphangiogenic factors may be more prominent in severe disease." (PMID 36999077, 2023). "Remodeling of airway lymphatic vessels is seen in asthma and in animal models has been shown to be mediated by VEGFC, VEGFD and TNF-alpha." (PMID 36999077, 2023).
scleroderma (2 papers, 2023 to 2025). Scleroderma is a rare autoimmune connective tissue disorder characterized by abnormal hardening of the skin and, sometimes, other organs. "They identified NTN1, VEGFD, MMP2, FGF2, and FNDC5 as potential players in how the ADSCs secretome may disrupt vascular and perivascular inflammation hubs in scleroderma and thereby promote angiogenesis and lymphangiogenesis." (PMID 40584563, 2025). "ADSCs may promote angiogenesis and especially lymphangiogenesis via VEGFD, MMP2, and Netrin 1, leading to revascularisation and normalisation of the disturbed microvascular architecture found in scleroderma." (PMID 37443817, 2023). "The few effector molecules that were identified, including NTN1, VEGFD, MMP2, FGF2, and FNDC5, provide evidence for the anti-fibrotic and anti-inflammatory effects of the ADSC secretome; however, these few factors cannot explain all observed effects on scleroderma skin after autologous fat grafting." (PMID 37443817, 2023).
apical periodontitis (1 paper, 2019). "Apart from vasculogenesis, it has been speculated that immune cells communicate with each other and with endothelial cells in human apical periodontitis through VEGF since clustered ELA2, CD68, CD3 and CD19 immune cells are VEGFA, VEGFR-2, VEGFR-3 and VEGFD positive." (PMID 31166414, 2019).
conjunctivitis (1 paper, 2023). Inflammation of the conjunctiva of the eye. "Moreover, there is a significant elevation of vascular endothelial growth factor-D (VEGF-D), cytokines, and inflammatory factors specifically seen in patients with ocular symptoms like conjunctivitis, critically ill patients, and those admitted to intensive care unit (ICU)." (PMID 36779162, 2023).
gingival enlargement (1 paper, 2024). "Both vascular endothelial growth factor D (VEGF-D) and KGF showed significant differences between patients taking amlodipine with gingival enlargement and those not taking amlodipine." (PMID 39204180, 2024).
invasive ductal breast carcinoma (1 paper, 2021). The most common type of invasive breast carcinoma, accounting for approximately 70% of breast carcinomas. "In addition, a positive correlation was shown between YKL‐40 and angiogenesis markers such as CD31, CD34, and VEGFD in invasive ductal breast carcinoma, which also suggests a link between YKL‐40 and angiogenesis." (PMID 34110111, 2021).
lymphoma (1 paper, 2020). A malignant (clonal) proliferation of B- lymphocytes or T- lymphocytes which involves the lymph nodes, bone marrow and/or extranodal sites. "In particular, we observed enhanced tumor angiogenesis, increasing pro-angiogenic and lymphangiogenic factors, such as VEGF, MMP-9, CCL2, and VEGFD, and a significant recruitment of tumor-associated macrophages in lymphomas of Ibtk+/-Eμ-myc compared to Ibtk+/+Eμ-myc mice." (PMID 32019112, 2020).
meningioma (1 paper, 2019). A generally slow growing tumor attached to the dura mater. "Compared to the control group, Grade I meningioma patients showed increased serum levels of amphiregulin (AREG), CCL24, CD69, prolactin, EGF, HB-EGF, caspase-3, and decreased levels of VEGFD, TGF-α, E-Selectin, BAFF, IL-12, CCL9, and GH." (PMID 31649887, 2019).
myofibromatosis (1 paper, 2021). "This could lead to the validation of VEGFD as a therapeutic target for selected cases of myofibromatosis." (PMID 33830670, 2021).
myxoid liposarcoma (1 paper, 2016). A liposarcoma characterized by the presence of round non-lipogenic primitive mesenchymal cells and small signet ring lipoblasts within a myxoid stoma with a branching vascular pattern. "Our finding that a VEGFR3 ligand trap, which binds VEGFC and VEGFD, markedly inhibited the growth of myxoid liposarcoma cells confirms that soluble angiogenic factors at least partly drive the growth of these cells." (PMID 27822137, 2016). "As the expression of VEGFR3 was elevated in the myxoid liposarcoma cell lines, it is possible that targeting VEGFR3 and/or the ligands VEGFC or VEGFD would be beneficial." (PMID 27822137, 2016).
oral cancer (1 paper, 2015). "In oral cancer, HMGB1 has been reported to promote lymphangiogenesis through the upregulation of vascular endothelial growth factor C (VEGF-C) and vascular endothelial growth factor D (VEGF-D), which might be linked to the transmigration of HMGB1." (PMID 25622595, 2015).
papillary adenocarcinoma (1 paper, 2017). A morphologic variant of adenocarcinoma. "The expression of VEGFD and FGF2 mRNA was significantly downregulated in lepidic and papillary adenocarcinomas when compared to adjacent normal lung tissues." (PMID 29137669, 2017).
primary lymphedema (1 paper, 2018). A congenital condition that results in swelling in the arms or legs, and can occur during adolescence or adulthood. "One possible explanation of a mild etiology of congenital primary lymphedema of Gordon is the possible compensation for the loss of VEGFC by other factors such as VEGFD since the mature form of human VEGFD binds both VEGFR2 and VEGFR3." (PMID 30071673, 2018).
Pulmonary hemorrhage (1 paper, 2022). Pulmonary hemorrhage is a bleeding within the lungs. "Moreover, VEGFD could avoid pulmonary hemorrhage because it has a pro-angiogenesis effect." (PMID 35941690, 2022).
respiratory distress syndrome (1 paper, 2023). "This is similar to the report that infants with severe respiratory distress syndrome had significantly lower VEGFD expression in the lungs than healthy infants." (PMID 37760250, 2023).
vulvar squamous cell carcinoma (1 paper, 2022). An invasive squamous cell carcinoma arising from the vulva. "Vascular endothelial growth factor D (VEGF-D) serum levels and correlation with the clinicopathological characteristics of vulvar squamous cell carcinoma (VSCC) patients from cohort A (N = 62)." (PMID 35463308, 2022).
tumor (281 papers, 2003 to 2026). "The genes FLT1, VEGFC, VWF, and VEGFD are closely linked to angiogenesis and vascular function, playing important roles in tumor angiogenesis." (PMID 38486263, 2024). "FIGF (also known as VEGFD) is a member of the VEGF family that has been implicated in tumor growth and lymphangiogenesis." (PMID 39330508, 2024). "VEGFC and VEGFD are usually expressed in primary human tumors or their related matrix and are secreted by tumor cells, immune cells and tumor-associated fibroblasts, while VEGFR3 is mainly expressed in LECs." (PMID 37803421, 2023). "A large number of studies have confirmed that the expression levels of VEGFC and VEGFD in many types of tumor cells are correlated with tumor-associated lymphangiogenesis, tumor cell invasion into lymphatic vessels, and LNM." (PMID 34552874, 2021). "The secreted prolymphangiogenic factor VEGFD is implicated in tumor growth; however, decreased serum levels of VEGFD were measured in patients with metastatic differentiated thyroid carcinoma." (PMID 32603365, 2020). "Others have suggested low VEGFD to be associated with worse prognosis, however we have seen the converse in advanced disease with poorer outcome associated with higher VEGFD in the primary tumour and we propose this is likely to be the result of up regulation of lymphangiogenesis." (PMID 23577117, 2013). "The VEGF protein family consists of VEGFA, VEGFB, VEGFC, VEGFD, and many others, some members of which are inducers of tumor lymphangiogenesis." (PMID 39866224, 2025). "VEGFC-VEGFCR3 and VEGFD-VEGFR3 signaling pathways are considered to be major drivers of tumor lymphangiogenesis and lymphatic remodeling." (PMID 39866224, 2025). "Overall, we revealed that tumor-secreted VEGFD interacted with VEGFR2, induced HEV dedifferentiation, and reduced lymphocyte homing, providing potential insights for the prevention and treatment of LN metastasis." (PMID 40693467, 2025). "This inflammatory response is part of a broader tumor-induced immune disruption, which also includes enhanced lymphangiogenesis and lymphatic remodeling, driven by VEGFC and VEGFD, facilitating tumor dissemination." (PMID 40563651, 2025). "The results reveal that the tumor weights of the control, VEGFD-OE, and VEGFD-OE+DC101 groups were 0.16 ± 0.01 g, 0.40 ± 0.05 g, and 0.29 ± 0.04 g, respectively." (PMID 40693467, 2025). "Previous studies report that VEGFA, VEGFC and VEGFD play roles in tumor metastasis by promoting tumor lymphangiogenesis or angiogenesis and further promoting LN metastasis." (PMID 40693467, 2025). "The tumor weights and volumes in the VEGFD-OE group were larger than those in the control group and in the VEGFD-OE+DC101 group." (PMID 40693467, 2025). "Injection of Tsc2-null tumor cells into the tail vein results in the growth of multiple lesions in the lungs, characterized by the expression of vascular endothelial growth factor D and the promotion of lymphangiogenesis." (PMID 39456169, 2024). "A higher expression of VEGF family genes, except VEGFD, was observed in tumor tissues than in normal tissues across most cancers." (PMID 37852616, 2023). "Western blot analysis also showed that the protein level of VEGFD was unusually decreased in tumor tissues compared with adjacent." (PMID 35941690, 2022). "The LC-BC CCPs formed have no more than 12 nodes and identified only seven genes (EDNRB, CDKN2A, VEGFD, FOS, GNG11, TGFBR2, and BIRC5) compromised in signaling pathways associated with the acquisition of tumor characteristics." (PMID 36101460, 2022). "Among these genes, AFP and VEGFD are well-known tumor biomarkers that have been extensively applied in the early screening of tumors." (PMID 35719915, 2022). "The H&E and IHC results of tumor tissue sections also showed that the protein abundance of VEGFD in tumor tissues was significantly lower than that in adjacent tissues." (PMID 35941690, 2022).
tumor (continued). "Tumors with high VEGFD expression showed increased microvessel density and an abundance of lymphatic vessels around and within the tumor." (PMID 35932027, 2022). "High mobility group box 1 (HMGB1) and vascular endothelial growth factor D (VEGFD) are associated with lymphangiogenesis and tumor metastasis in GC." (PMID 36120367, 2022). "Conversely, CRART16-shRNA had the opposite effects on tumor growth, tumor weights, angiogenesis, and expressions of c-Fos, VEGFD, and CD31." (PMID 35537818, 2022). "ReactomeFIViz enrichment analysis in Cytoscape showed an association of seven (EDNRB, CDKN2A, VEGFD, FOS, GNG11, TGFBR2, and BIRC5) of the forty-four nodes of the LC-BC CCPs with signaling pathways related with the acquisition of tumor characteristics." (PMID 36101460, 2022). "Vascular endothelial growth factor D (VEGF-D) is considered a regulator of lymphangiogenesis involved in tumor spread via lymphatic vessels." (PMID 35463308, 2022). "We observed a robust expression of VEGFD by immunofluorescence on the corresponding tumour sections." (PMID 33830670, 2021). "The analyses of the transcriptomic profiles of our samples evidenced a robust enrichment in multiple angiogenic pathways, supporting the production of bioactive VEGFD by these tumours." (PMID 33830670, 2021). "The stained tissue sections demonstrated that the expression of VEGFD was robust in the P38 tumour sample, bearing the COL4A1‐VEGFD gene fusion, compared to patient P46, used as negative control." (PMID 33830670, 2021). "We thus questioned classical activators of VEGFR3 such as VEGFC and VEGFD, which can be secreted by aggressive tumor cells and play key roles in neolymphangiogenesis in cancer." (PMID 34762341, 2021). "Quantitative analysis of our RNA sequencing data showed that the strong expression of COL4A1 in myofibroma enables the expression of VEGFD specifically in tumours harbouring the COL4A1‐VEGFD fusion gene." (PMID 33830670, 2021). "For example, numerous works on xenogeneic tumor transplantation models in mice have demonstrated that targeting the VEGFC-VEGFR3 and VEGFD-VEGFR3 axis can inhibit tumor lymphangiogenesis, lymphadenopathy, and lymph node metastasis." (PMID 33013360, 2020). "VEGFD expression was examined in cHL and a correlation was reported between the VEGFD and the elevated number of tumor microvessels." (PMID 31824854, 2019). "We found the strongest correlation of miRNA expression with VEGFD expression in tumor samples, which confirms our cell line findings of high expression of VEGFD in miRNA high cell lines." (PMID 31277414, 2019). "For the first time here, we report that VEGFD expression is significantly high in tumour samples compared with control tissue." (PMID 31277414, 2019). "Vascular endothelial growth factor C (VEGF-C) and vascular endothelial growth factor D (VEGF-D) can also increase the vascular permeability of tumor cells and change the adhesive properties of the lymphatic endothelium." (PMID 30564284, 2018). "Vascular endothelial growth factor‐D (VEGF‐D) is an angiogenic and lymphangiogenic glycoprotein that facilitates tumour growth and distant organ metastasis." (PMID 27957793, 2017). "VEGF family members, including VEGFA, VEGFB, VEGFC, and VEGFD, are secreted by autocrine stimulation of tumor cells as well as through paracrine influences of the proangiogenic tumour microenvironment." (PMID 25810565, 2015). "The VEGFD/VEGFR2 axis is a crucial signaling pathway that governs tumor angiogenesis." (PMID 40693467, 2025). "First, we analyzed the expression of VEGFD to interrogate the role of VEGFD in the specific tumor." (PMID 35941690, 2022). "One of the most studied molecular systems in the regulation of tumor lymphangiogenesis is based on the interaction between vascular endothelial growth factor D (VEGF-D) and the corresponding VEGF receptor 3 (VEGFR-3), commonly expressed on the surface of lymphatic endothelial cells." (PMID 35463308, 2022).